AMBP (alpha-1-microglobulin/bikunin precursor)
Description:
[Alpha-1-microglobulin]: Antioxidant and tissue repair protein with reductase, heme-binding and radical-scavenging activities. Removes and protects against harmful oxidants and repairs macromolecules in intravascular and extravascular spaces and in intracellular compartments. Intravascularly, plays a regulatory role in red cell homeostasis by preventing heme- and reactive oxygen species-induced cell damage. Binds and degrades free heme to protect fetal and adult red blood cells from hemolysis. Reduces extracellular methemoglobin, a Fe3+ (ferric) form of hemoglobin that cannot bind oxygen, back to the Fe2+ (ferrous) form deoxyhemoglobin, which has oxygen-carrying potential. Upon acute inflammation, inhibits oxidation of low-density lipoprotein particles by MPO and limits vascular damage. Extravascularly, protects from oxidation products formed on extracellular matrix structures and cell membranes. Catalyzes the reduction of carbonyl groups on oxidized collagen fibers and preserves cellular and extracellular matrix ultrastructures. Importantly, counteracts the oxidative damage at blood-placenta interface, preventing leakage of free fetal hemoglobin into the maternal circulation. Intracellularly, has a role in maintaining mitochondrial redox homeostasis. Bound to complex I of the respiratory chain of mitochondria, may scavenge free radicals and preserve mitochondrial ATP synthesis. Protects renal tubule epithelial cells from heme-induced oxidative damage to mitochondria. Reduces cytochrome c from Fe3+ (ferric) to the Fe2+ (ferrous) state through formation of superoxide anion radicals in the presence of ascorbate or NADH/NADPH electron donor cofactors, ascorbate being the preferred cofactor. Has a chaperone role in facilitating the correct folding of bikunin in the endoplasmic reticulum compartment (By similarity). [Inter-alpha-trypsin inhibitor light chain]: Kunitz-type serine protease inhibitor and structural component of extracellular matrix with a role in extracellular space remodeling and cell adhesion. Among others, has antiprotease activity toward kallikrein, a protease involved in airway inflammation; inhibits GZMK/granzyme, a granule-stored serine protease involved in NK and T cell cytotoxic responses; and inhibits PLG/plasmin, a protease required for activation of matrix metalloproteinases. As part of I-alpha-I complex, provides for the heavy chains to be transferred from I-alpha-I complex to hyaluronan in the presence of TNFAIP6, in a dynamic process that releases free bikunin and remodels extracellular matrix proteoglycan structures. Free bikunin, but not its heavy chain-bound form, acts as potent protease inhibitor in airway secretions. Part of hyaluronan-rich extracellular matrix that surrounds oocyte during cumulus oophorus expansion, an indispensable process for proper ovulation (By similarity). Also inhibits calcium oxalate crystallization. [Trypstatin]: Kunitz-type serine protease inhibitor. Has high catalytic efficiency for F10/blood coagulation factor Xa and may act as an anticoagulant by inhibiting prothrombin activation. Inhibits trypsin and mast cell CMA1/chymase and tryptase proteases.
Synonyms: HCP; ITIL; UTI; EDC1; HI30; IATIL; ITILC; A1M; ITI
Tractability: Small molecule: a structure with a bound ligand is known. Antibody: UniProt places it where antibodies can reach, with high confidence; its Gene Ontology location is reachable by antibodies, with high confidence; UniProt predicts a signal peptide or a membrane-spanning region. PROTAC: its protein half-life has been measured.
Gene: Protein-coding gene on chromosome 9 (114,060,127 to 114,080,970, reverse strand). Ensembl gene ENSG00000106927.
Subcellular location: Secreted (Alpha-1-microglobulin); Endoplasmic reticulum; Cytoplasm, cytosol; Cell membrane; Nucleus membrane; Mitochondrion inner membrane; Secreted, extracellular space, extracellular matrix; Secreted (Inter-alpha-trypsin inhibitor light chain)
Subcellular location (Human Protein Atlas): Vesicles; Cytosol; Golgi apparatus; Predicted to be secreted
Pathways (Reactome):
Vesicle-mediated transport: Scavenging of heme from plasma
Gene Ontology:
Molecular function: carbohydrate binding; heme binding; IgA binding; protein binding; protein homodimerization activity; calcium channel inhibitor activity; calcium oxalate binding; serine-type endopeptidase inhibitor activity
Biological process: cell adhesion; female pregnancy; heme catabolic process; negative regulation of immune response; negative regulation of JNK cascade; protein catabolic process
Cellular component: blood microparticle; endoplasmic reticulum; extracellular exosome; extracellular matrix; extracellular region; nuclear membrane; plasma membrane; cell surface; cytosol; mitochondrial inner membrane
Genetic constraint (gnomAD): Loss-of-function variants: 39 observed, 50.07 expected, observed/expected ratio (o/e) 0.78, 90% interval 0.6 to 1.02. The upper end of that interval is the gene's LOEUF score, 1.02, which puts it in group 4 of 6, group 1 being the genes least tolerant of losing a copy. Missense variants: 475 observed, 483.66 expected, observed/expected ratio (o/e) 0.98, 90% interval 0.91 to 1.06. Synonymous variants: 174 observed, 184.83 expected, observed/expected ratio (o/e) 0.94, 90% interval 0.83 to 1.07.
Homologues: Orthologues: macaque AMBP (95% identical), chimpanzee AMBP (93% identical), guinea pig AMBP (76% identical), mouse Ambp (75% identical), rat Ambp (75% identical), pig AMBP (73% identical), dog AMBP (69% identical), tropical clawed frog ambp (54% identical), zebrafish ambp (46% identical), Drosophila melanogaster CG7565 (17% identical), Caenorhabditis elegans C02F12.5 (11% identical), Caenorhabditis elegans Y55F3BR.2 (11% identical), and 1 more. Paralogues in human: WFIKKN1 (21% identical), WFIKKN2 (20% identical), SPINT1 (19% identical), TFPI (19% identical), KIAA0319L (17% identical), KIAA0319 (16% identical), TFPI2 (15% identical), WFDC8 (12% identical), SPINT2 (12% identical), EPPIN (10% identical), LRP11 (9% identical), SPINT4 (7% identical), and 1 more.